VIM-AS1 (VIM antisense RNA 1)
Gene: Long non-coding RNA gene on chromosome 10 (17,214,239 to 17,230,029, reverse strand). Ensembl gene ENSG00000229124.
Diseases named in the same sentence as VIM-AS1 in open-access papers:
VIM-AS1 is named in the same sentence as 14 diseases in open-access papers, as found by Europe PMC text mining. Sharing a sentence is not in itself a finding about the gene and the disease. The quoted sentences say what the papers report.
bladder cancer (3 papers, 2021 to 2022). "VIM-AS1 knockdown in T24 cells significantly suppressed the migration and invasion of high-metastatic bladder carcinoma cells, while VIM-AS1 overexpression in RT24 cells promoted the migration and invasion of low-metastatic bladder carcinoma cells." (PMID 33902589, 2021). "Similarly, the expression of VIM-AS1 was markedly elevated in bladder cancer, and VIM-AS1 acts as a sponge for miR-655 to promote bladder cancer cell metastasis by regulating EMT40." (PMID 35787661, 2022). "Thus, we speculate that VIM-AS1 may exert a pivotal effect in bladder cancer cell EMT and metastasis." (PMID 33902589, 2021). "By silencing VIM-AS1 in high-metastatic bladder cancer cells and overexpressing VIM-AS1 in low-metastatic bladder cancer cells, we investigated the detailed cellular functions of VIM-AS1 on the migration and invasion ability of bladder cancer cells." (PMID 33902589, 2021). "In both cell lines, VIM-AS1 and Vimentin expression levels were prominently occasioned by TGFβ1 incentive in a concentration-dependent manner, indicating that VIM-AS1 is related to EMT in bladder cancer and cancer metastasis." (PMID 33902589, 2021). "Via serving as a ceRNA for miR-655, VIM-AS1 competed with ZEB1 for miR-655 binding, therefore eliminating miR-655-mediated suppression of ZEB1, finally affecting EMT in both high- and low-metastatic bladder cancer cells and cancer cell metastasis." (PMID 33902589, 2021). "By acting as a ceRNA for miR-655, VIM-AS1 competed with ZEB1 for miR-655 binding, therefore eliminating the miR-655-mediated suppression of ZEB1, finally promoting EMT in both high- and low-metastatic bladder cancer cells and enhancing cancer cell metastasis." (PMID 33902589, 2021). "More importantly, the effects of VIM-AS1 on both cell lines were significantly reversed by miR-655, indicating that VIM-AS1 acts as a ceRNA to competitively bind to miR-655, therefore rescuing ZEB1 expression and promoting EMT and metastasis in bladder cancer cells." (PMID 33902589, 2021). "Since VIM-AS1 was predicted by an online tool to target miR-655, herein, we hypothesized that VIM-AS1 might act as a competing endogenous RNA (ceRNA) for miR-655 to offset miR-655-mediated inhibition of ZEB1, therefore modulating bladder cancer cell EMT." (PMID 33902589, 2021).
gastric cancer (2 papers, 2021 to 2024). A primary or metastatic malignant neoplasm involving the stomach. "VIM antisense RNA 1 (VIM-AS1) expression enhanced tumorigenic pathways by downregulating miR-8052 expression and increasing expression of Fzd1 in human gastric cancer (GC) tissue." (PMID 34671643, 2021).
prostate carcinoma (2 papers, 2021 to 2024). A carcinoma that arises from epithelial cells of the prostate gland. "SHI identified VIM-AS1 as a key LncRNA regulator; VIM-AS1 overexpression reduced the sensitivity to enzalutamide treatment, which plays a regulatory role in prostate cancer proliferation as well as enzalutamide sensitivity through the VIM-AS1/IGF2BP2/HMGCS1 axis." (PMID 39655078, 2024).
colon cancer (1 paper, 2024). "In colon cancer, VIM-AS1 upregulation is correlated with cancer progression and poor survival, whereas VIM-AS1 downregulation suppresses the EMT and migration of colon cancer cells." (PMID 39617786, 2024).
liver cancer (1 paper, 2024). An epithelial or non-epithelial malignant neoplasm that arises from the liver. "The researchers discovered that hypermethylation of a specific DNA region in the VIM-AS1 gene is linked to poor prognosis in liver cancer." (PMID 39617786, 2024).
lung adenocarcinoma (1 paper, 2023). A carcinoma that arises from the lung and is characterized by the presence of malignant glandular epithelial cells. "Results showed that VIM-AS1 was expressed with low levels in lung adenocarcinoma compared to the normal samples." (PMID 37283796, 2023). "We overexpressed the VIM-AS1 mRNA in A549, the classical lung adenocarcinoma cell line." (PMID 37283796, 2023).
type 2 diabetes (1 paper, 2020). "Long non-coding RNA (lncRNA) VIM Antisense RNA 1 (VIM-AS1) has been reported to be correlated with type 2 diabetes (T2D) susceptibility, while the roles of this lncRNA in T2D and its complications remain unclear." (PMID 32447557, 2020).
tumor (7 papers, 2021 to 2026). "In cancers with high beta values for cg02746869, such as LIHC, VIM-AS1 expression was downregulated, whereas in tumor types with low beta values, such as CHOL, VIM-AS1 expression was upregulated." (PMID 39617786, 2024). "Overexpression of VIM-AS1 mitigated the tumor malignancy and tumorigenesis of HCC both in vitro and in vivo." (PMID 39617786, 2024). "The lncRNA VIM-AS1 has been shown in numerous studies to regulate the growth and metastasis of various tumor cells." (PMID 36160015, 2022). "Consistent with previous studies, Vimentin expression was significantly upregulated in tumor tissues, and was positively correlated with VIM-AS1 expression." (PMID 33902589, 2021). "More importantly, VIM-AS1 expression was the most upregulated in tumor tissues, especially in metastatic tumor tissues." (PMID 33902589, 2021). "In line with the viability data, VIM-AS1 knockdown alone significantly decreased the mitochondrial potential of tumor cells, which was further enhanced when combined with treatment with Dox or Taxol, suggesting a more potent induction of cell death when VIM-AS1 was silenced." (PMID 41556346, 2026). "Moreover, reducing VIM-AS1 impaired significantly the TGF-β-induced invasion of multiple tumor cell types through Matrigel, in comparison to their respective controls." (PMID 41556346, 2026). "However, how VIM-AS1 regulates tumor cell apoptosis is barely known." (PMID 37283796, 2023). "Notably, studies have revealed that VIM-AS1 also interferes with tumor regulation." (PMID 37543428, 2023). "In line with TGF-β inducing VIM-AS1 v.2 expression in several cancer cells, we found a positive and significant correlation between TGFB1 mRNA and VIM-AS1 v.2 expression in different tumor types across TCGA dataset." (PMID 41556346, 2026).
cancer (4 papers, 2021 to 2026). A tumor composed of atypical neoplastic, often pleomorphic cells that invade other tissues. "VIM-AS1 function has also been linked to EMT induction in some cancer models by acting as competing endogenous (ce) RNA." (PMID 41556346, 2026). "Independent functions of VIM-AS1 have been reported in cancer cells, ranging from ceRNA function to regulation of mRNA stability and DNA-based transcriptional control." (PMID 41556346, 2026). "By analyzing the two major transcripts generated by the VIM-AS1 gene, we found that TGF-β induced VIM-AS1 v.2, and to a lesser extent v.1, in a large panel of normal, immortalized and cancer cell lines of diverse tissue types." (PMID 41556346, 2026). "Considering that VIM-AS1 expression is reduced in HCC, we focused on the functions of genes downregulated upon VIM-AS1 upregulation to understand their inhibitory effects on cancer progression." (PMID 39617786, 2024). "Consistent with in vivo observations, VIM-AS1 and Vimentin expression levels were dramatically upregulated in carcinoma cells and were more upregulated in high-metastatic cancer cell lines." (PMID 33902589, 2021). "A recent report implicating VIM-AS1 in TGF-β-induced tissue fibrosis, suggests that our findings may have broader significance in human diseases beyond cancer, where TGF-β signaling plays key roles, such as fibrotic and chronic inflammatory conditions." (PMID 41556346, 2026). "Regarding cellular functions, VIM-AS1 overexpression remarkably promoted, whereas miR-655 overexpression inhibited RT24 cell invasiveness and migration capability; the impacts of VIM-AS1 overexpression on carcinoma cells were significantly abolished by miR-655 overexpression." (PMID 33902589, 2021).
VIM-AS1 also shares sentences with these, for which no sentence is quoted: colorectal cancer (2 papers); breast carcinoma (1); diabetic retinopathy (1); hepatocellular carcinoma (1); oral carcinoma (1).